FADS1 (fatty acid desaturase 1)
Diseases named in the same sentence as FADS1 in open-access papers (continued):
Sharing a sentence is not in itself a finding about the gene and the disease.
Hypertension (7 papers, 2013 to 2023). The presence of chronic increased pressure in the systemic arterial system. "FADS1 gene variants and cardiovascular diseases (CVD) or stroke for which hypertension is a major risk factor suggested a role of the rs174546 SNP." (PMID 28732058, 2017). "Fatty acid desaturase 1 rs174546 (C>T) did not associate with hypertension." (PMID 29989339, 2018). "FADS1 rs174546 (C>T) did not associate with hypertension or lipids." (PMID 29989339, 2018). "Based on our results, therefore, rs174556 in the FADS1 has a significant role in the development of ACS, especially in subjects with hypertension." (PMID 23555103, 2013).
steatosis (7 papers, 2014 to 2025). Increased lipid within the cytoplasm of cells. "After correcting for multiple testing, only one CpG site annotated to FADS1 showed significant correlation to steatosis grade and fibrosis stage (cg16213375)." (PMID 30654845, 2019). "Moreover the lipogenic genes (SREBF1 and FADS1) found to be regulated in the present study are reported to be involved in steatosis but most of these studies are related to nutritionally induced steatosis." (PMID 25470483, 2014). "Additionally, a comparison between drugs causing phospholipidosis and/or steatosis revealed 26 genes to be regulated in common including 4 signature genes to predict DIS (PKLR, GK, FABP7 and FADS1)." (PMID 25470483, 2014). "In fact, the activities of fatty acid desaturase 1 (FADS1) and elongase 6 (ELOVL6) were decreased in MASH patients, and their role in the progression of simple steatosis to MASH is a subject currently under intense investigation." (PMID 40649925, 2025). "Furthermore, a comparison between drugs inducing phospholipidosis and/or steatosis uncovered 26 commonly regulated genes, including from the signature markers (PKLR, GK, FABP7 and FADS1)." (PMID 38791241, 2024). "From this CRISPR screen, FADS2 (but not FADS1) emerged as a critical player in steatosis." (PMID 36823355, 2023).
asthma (6 papers, 2022 to 2025). "The colocalization analysis suggested that the three candidate metabolite traits and asthma likely share causal variants within the FADS1 locus." (PMID 37221513, 2023). "Cis-eQTL-MR and colocalization analysis were also performed to determine the association between RNA expression of FADS1 and asthma." (PMID 37221513, 2023). "The replication analysis also obtained consistent results, and the Cis-eQTL-MR demonstrated that the higher genetically predicted expression level of the FADS1 gene was causally associated with a lower risk of asthma." (PMID 37221513, 2023). "First and foremost, the demonstrated association of asthma with the candidate metabolite in MR is instrumented by the FADS1 gene, which is one of the most pleiotropic loci." (PMID 37221513, 2023). "The significance of the FADS1 rs174556 SNP with pathological manifestations has been addressed where rs174556 SNP was reported to be associated with asthma, pregnancy duration and birthweight, and blood concentrations of lipids." (PMID 36806496, 2023). "Overall, our study demonstrated that the genetically predicted traits related to concentrations of serum long-chain unsaturated fatty acids were negatively associated with the risk of asthma, but this association was genetically instrumented by FADS1 polymorphisms." (PMID 37221513, 2023). "During our further colocalization analysis, evidence of shared causal variants within the FADS1 locus was found between asthma and FADS1, which means the locus on FADS1 can potentially affect the occurrence of asthma by regulating the biological process of the FADS1 gene expression." (PMID 37221513, 2023). "In addition, the cis-eQTL-MR and colocalization analyses demonstrated a causal association and shared causal variants between FADS1 expression and asthma." (PMID 37221513, 2023). "In addition, the result of the colocalization analysis suggested that FADS1 and asthma likely share causal variants within the FADS1 locus (PP.H4 = 0.978)." (PMID 37221513, 2023). "Further, we performed colocalization analysis to examine the pleiotropy of variants within the fatty acid desaturase 1 (FADS1) locus between the significant metabolite traits and the risk of asthma." (PMID 37221513, 2023). "FADS1 and FADS2 were linked to asthma in several previous studies." (PMID 40676019, 2025). "Cis-eQTL-MR found that the genetically predicted expression level of FADS1 gene was negatively associated with the risk of asthma, with no presence of heterogeneity or pleiotropy detected by the MR-Egger intercept and the MR-PRESSO method (Pintercept = 0.304, PMR-PRESSO global test = 0.36)." (PMID 37221513, 2023). "This includes meQTL SNP rs174548 in FADS1, with strongest effect in CD8T cells, linking fatty acid metabolism with immune dysregulation and asthma." (PMID 34980917, 2022). "Notably, decreased activity of FADS1 and FADS2 (fatty acid desaturase 1 and 2) are markers of asthma progression." (PMID 37680636, 2023). "Finally, we used interaction analyses to identify population and lineage specific meQTLs, including rs174548 in FADS1, with strongest effect in CD8T cells, thus linking fatty acid metabolism with immune dysregulation and asthma." (PMID 34980917, 2022).
Hepatic steatosis (6 papers, 2014 to 2025). Steatosis is a term used to denote lipid accumulation within hepatocytes. "The minor ancestral allele, which is characterized by lower FADS1 expression, has been implicated to confer increased metabolic risk and increased liver steatosis." (PMID 39021601, 2024). "Given that FADS1 activity is reduced in MASLD patients and FADS1 deficiency worsens hepatic steatosis and cholesterol metabolism, we hypothesize that overexpression of Fads1 in hepatocytes improves MASLD and metabolic phenotypes." (PMID 38732052, 2024). "In another microarray study, FADS1 was also found to be repressed where it is predicted to play a role in hepatic steatosis." (PMID 25470483, 2014).
lung cancer (6 papers, 2019 to 2025). A malignant neoplasm involving the lung. "The rs174549 was in high LD with rs174548 (r2 = 0.98), which was proven to be correlated with lung cancer risk by regulating FADS1 gene expression in liver tissues (β = −0.23, P = 2.20 × 10−7) and plasma levels of polyunsaturated fatty acids (PUFAs) according to our recent study." (PMID 32010612, 2019). "For instance, expression levels of FADS1 in memory T cells showed little evidence to support an effect on lung cancer at 0 h but showed much stronger effects at 16 h, 40 h, and 5 d." (PMID 41216857, 2025). "It was found that the GG allele of rs174548 was associated with reduced FADS1 expression (but not FADS2) and that omega-6 PUFAs contribute more to lung cancer risk than omega-3, with a stronger protective effect observed in women." (PMID 40430008, 2025). "There was strong evidence for colocalisation of lung cancer with FADS1 gene expression in adipose subcutaneous tissue (PPH4 = 96%) but not with FADS1 gene expression in lung tissue or with PUFA desaturase activity (PPH4 < 70%)." (PMID 37086649, 2023). "A gene‐cancer combination, regardless of the gene expression profiles, e.g., FADS1‐lung cancer." (PMID 41216857, 2025).
non-alcoholic fatty liver disease (6 papers, 2022 to 2024). "Notably, the dysregulation in FADS1 influences hepatic lipid homeostasis by modulating the PPARα-FGF21 axis and a decreased hepatic FADS1 expression, associated with low levels of long-chain PUFAs, have been detected in subjects with nonalcoholic fatty liver disease (NAFLD)." (PMID 36140410, 2022).
atherosclerosis (5 papers, 2017 to 2024). A disease characterized by the build-up of fatty material and calcium deposition in the arterial wall resulting in partial or complete occlusion of the arterial lumen. "Future studies should focuson how macrophages regulate their metabolism of PUFAs, and more studies areneeded to assess the impact of FADS1 on atherosclerosis developmentunder various metabolic conditions." (PMID 39076540, 2024). "Studies have shown that mice of different genetic backgrounds present differentoutcomes after FADS1 knockdown and that the percentage of PUFAs in thediet affects the survival and progression of atherosclerosis in mice." (PMID 39076540, 2024).
atopic eczema (5 papers, 2010 to 2025). A common chronic pruritic inflammatory skin disease with a strong genetic component. "Individuals carrying polymorphisms of the FADS1 are linked to a lower prevalence of allergic rhinitis and atopic eczema." (PMID 39938773, 2025). "A previous study in adults found protective associations of carriers of minor alleles of the FADS1 FADS2 gene cluster with allergic rhinitis and atopic eczema." (PMID 20948998, 2010). "Some of lipid metabolic genes discovered in our analysis were also reported as declined genes in patients with psoriatic (ACSBG1, ALOX15B, ELOVL3, FADS1, FADS2, and THRSP) or atopic dermatitis (CYP4F8, ELOVL3, FADS1, FADS2, FAR2, and HAO2)." (PMID 30021930, 2018).
Crohn disease (5 papers, 2013 to 2022). A gastrointestinal disorder characterized by chronic inflammation involving all layers of the intestinal wall, noncaseating granulomas affecting the intestinal wall and regional lymph nodes, and transmural fibrosis. "For instance, polymorphisms in the fatty acid desaturase 1 (FADS1) locus are associated with Crohn's disease and are furthermore suspected to play a role in cardiovascular disorders through association with cholesterol and triglycerides." (PMID 23414815, 2013). "Children who consume a diet with a higher ratio of n-6:n-3 PUFA intake may be more susceptible to Crohn’s disease if they also carry SNPs in Cytochrome P450 Family 4 Subfamily F Member 3 (CYP4F3), Fatty Acid Desaturase 1 and 2 (FADS1, FADS2)." (PMID 35450067, 2022).
esophageal squamous cell carcinoma (5 papers, 2018 to 2023). Esophageal squamous cell carcinoma (ESCC) is a type of esophageal carcinoma (EC) that can affect any part of the esophagus, but is usually located in the upper or middle third. "In patients with esophageal squamous cell carcinoma, a lower expression of FADS1 was associated with improved prognosis." (PMID 32392704, 2020). "Decreased expression of FADS1 benefits development and growth of cancer cells, whereas increased expression was observed to be a protective factor in esophageal squamous cell carcinoma (ESCC)." (PMID 30175151, 2018). "Moreover, FADS1, which catalyzes DGLA to AA, was also increasingly expressed in esophageal squamous cell carcinoma and regulated cancer cell invasion through the Akt/mTOR pathway." (PMID 38136676, 2023).
schizophrenia (5 papers, 2013 to 2025). A major psychotic disorder characterized by abnormalities in the perception or expression of reality. "The FADS1 and FADS2 variants used in this study satisfied HWE within the schizophrenia and bipolar populations as well as in the combined sample (all P > 0.1)." (PMID 24455201, 2013). "Therefore, it was reassuring to identify the chr17q21.31, chr3p21.1, and FADS1/FADS2 loci, which are associated with schizophrenia, cognition, and household income; cognition; and metabolic traits, respectively, as linking these co-occurring traits to ADHD." (PMID 40000109, 2025). "Similarly, a network analysis of ADHD-associated genetic variants identified genomic regions (e.g., chr17q21.31, FADS1/FADS2, chr3p21.1) at the intersection of ADHD with co-occurring traits (e.g., schizophrenia, metabolic traits, and intelligence)." (PMID 40000109, 2025).
Stroke (5 papers, 2017 to 2026). Sudden impairment of blood flow to a part of the brain due to occlusion or rupture of an artery to the brain. "Similar to our findings, the minor allele of FADS1 rs174547, a SNP in high linkage disequilibrium with the 3 identified variants, was associated with lower odds of stroke in a previous Mendelian randomization study in a predominantly European population." (PMID 36193932, 2022).
glioblastoma (4 papers, 2018 to 2025). The most malignant astrocytic tumor (WHO grade IV). "Consistent with previous findings that miR-1908 is regulated by its own transcription unit rather than co-regulated with its host gene FADS1, we found that expressions of miR-1908 and FADS1 are negatively correlated/uncorrelated in glioblastoma and ovarian cancer (R = −0.12, 0.01; FDR = 0.01, 0.87)." (PMID 30785618, 2018). "Three studies focused on PUFA status and genetic variation in FADS1/FADS2 genes, two on prostate cancer and one on glioblastoma multiforme." (PMID 40430008, 2025). "Another case–control study examined the expression of desaturases (FADS1, FADS2, and SCD) in glioblastoma tumors from 28 patients." (PMID 40430008, 2025). "However, FADS1 expression may depend on the type of glioblastoma cell." (PMID 37046844, 2023). "Interestingly, the higher FADS1 expression was significantly associated with better OS (HR=0.702; 95% CI 0.604-0.816; P<0.001) and DFS (HR=0.706; 95% CI 0.615-0.809; P<0.001) among all brain cancers which include Lower grade glioma (LGG) and Glioblastoma multiforme (GBM)." (PMID 36046053, 2022). "The expression level of FADS1 in glioblastoma tumors does not differ from that of nontumor brain tissue." (PMID 37046844, 2023). "In glioblastoma cancer stem cells, FADS1 expression is higher than in nonstem cancer cells, and its activity is critical for cell viability and self-renewal." (PMID 37046844, 2023). "Similar to FADS1, FADS2 expression may depend on the type of glioblastoma cell." (PMID 37046844, 2023).
ischemic stroke (4 papers, 2019 to 2026). A stroke disorder caused by obstruction of blood flow to the brain, due to thrombotic (local blood clot formation) or embolic (due to a blood clot or other material traveling from another site) event. "There was a statistically significant inverse association between the minor allele of rs174547 (minor allele frequency of 0.34 in UK Biobank) in FADS1 and three of the 15 CVDs, including any ischemic stroke, large-artery stroke, and venous thromboembolism." (PMID 31817859, 2019). "Associations between FADS1/FADS2 variants and complex conditions such as MetS, T2DM, and cardiovascular disease (e.g., acute coronary syndromes, CAD, and ischemic stroke) have likewise been described." (PMID 35736500, 2022). "FADS1 (rs174546) and FADS2 (rs174601) were linked to CAD and ischemic stroke." (PMID 35736500, 2022).
kidney cancer (4 papers, 2022 to 2025). Primary or metastatic malignant neoplasm involving the kidney. "Previously we also demonstrated that FADS1 expression is significantly associated with poor patient survival among all three independent cohorts of kidney cancer patients in TCGA." (PMID 40121894, 2025). "Recently, we showed that FADS1 gene expression is associated with poor patient survival in multiple cancer types, and especially in kidney cancers." (PMID 38586033, 2024). "We have previously demonstrated that FADS1 expression is significantly associated with poor patient survival among all three independent cohorts of kidney cancer patients in TCGA." (PMID 38586033, 2024). "The co-expression gene profiles as well as the TME-related tumoral cell infiltration data also demonstrated an opposite direction in their association with FADS1 expression between kidney cancers and brain tumors." (PMID 36046053, 2022). "To further validate whether FADS1 is causally involved in cancer cell proliferation, we chose a renal cell carcinoma cell line 786-O since FADS1 mRNA level shows the most significant correlation with patient survival in kidney cancers." (PMID 36046053, 2022). "Our previous research has demonstrated the significant role of FADS1 in cancer biology and patient survival, especially in kidney cancers." (PMID 40121894, 2025). "Our previous research has demonstrated the significant role of FADS1 in cancer survival, especially in kidney cancers." (PMID 38586033, 2024). "Our previous analysis has shown an increased FADS1 expression in kidney cancers with a pattern of expression level in normal tissues<primary tumors<metastatic tumors<recurrent tumors." (PMID 38586033, 2024). "Our previous research has demonstrated that increased FADS1 gene expression is significantly correlated with reduced cancer patient survival among multiple types of cancers, and especially in kidney cancer patients." (PMID 38586033, 2024). "We also found that in kidney cancers, FADS1 mRNA levels demonstrated a significantly gradient elevation from adjacent normal tissue, primary RCC tumors, metastatic tumors to recurrent tumors, highlighting its potential role in cancer biology and disease progression." (PMID 40121894, 2025). "Combined with the observations from our current study, these data may reflect an escalating dependence of FADS1 expression in response to an increased ER stress level during the progression of kidney cancers." (PMID 38586033, 2024).
prostate carcinoma (4 papers, 2006 to 2025). A carcinoma that arises from epithelial cells of the prostate gland. "Here, the authors analyse 24 circulating fatty acids in Ghanaian, African American, and European American men, and explore the associations with socio-demographic factors, diet, FADS1/2 locus, and prostate cancer." (PMID 37468456, 2023). "The mRNA expression level of FADS1 was significantly decreased in the PPAT of obese with prostate cancers in our previous study using qRT-PCR." (PMID 29692867, 2018). "Nonetheless, the FADS1/2 locus has not been previously linked to prostate cancer in most studies." (PMID 37468456, 2023).
acute coronary syndrome (3 papers, 2013 to 2023). Signs and symptoms related to acute ischemia of the myocardium secondary to coronary artery disease. "An alternative/minor allele of FADS1 rs174537 was linked to T2DM in an Iranian population, and FADS1 rs74556 and FADS2 rs174617 have been linked with acute coronary syndromes." (PMID 35736500, 2022). "The purpose of this study is to analyze the relationship between the polymorphisms of fatty acid desaturase 1 (FADS1), fatty acid desaturase 2 (FADS2), and elongation of very long-chain fatty acids-like 2 (ELOVL2) and acute coronary syndrome (ACS) in Chinese Han population." (PMID 23555103, 2013).
aortic stenosis (3 papers, 2020 to 2024). Aortic valve stenosis is a aortic valve disease caused by the incomplete opening of the aortic valve. "Aortic stenosis contributes to cardiovascular mortality and morbidity, andrecent studies found that FADS1 SNP is associated with the risk ofaortic stenosis." (PMID 39076540, 2024). "In this genome-wide association study of 44 703 participants, each copy of a FADS1/2 (fatty acid desaturase) genetic variant was associated with a 13% decrease in the odds of aortic stenosis." (PMID 32186652, 2020). "Furthermore, large-scale genome-wide associated studies identified a variant in the palmdelphin (PALMD) and fatty acid desaturase 1/2 (FADS1/2) locus linked to aortic stenosis and bicuspid aortic valve." (PMID 36359785, 2022).
bladder cancer (3 papers, 2021 to 2025). "A recent TCGA based study has suggested that bladder cancer patients with high FADS1 expression have a poor prognosis." (PMID 34438249, 2021). "Further investigation is warranted to elucidate how AhR signaling regulates the expression or activity of FADS1 and FADS2 in bladder cancer, which may help uncover the mechanisms underlying the altered MUFA/PUFA ratio observed in our study." (PMID 40557796, 2025). "The in vitro study further shows that overexpression of FADS1 could lead to bladder cancer proliferation, whereas the FADS1 knockdown could arrest the cell cycle." (PMID 34438249, 2021).